RIPK1 (receptor interacting serine/threonine kinase 1)
Description:
Serine-threonine kinase which is a key regulator of TNF-mediated apoptosis, necroptosis and inflammatory pathways. Exhibits kinase activity-dependent functions that regulate cell death and kinase-independent scaffold functions regulating inflammatory signaling and cell survival. Has kinase-independent scaffold functions: upon binding of TNF to TNFR1, RIPK1 is recruited to the TNF-R1 signaling complex (TNF-RSC also known as complex I) where it acts as a scaffold protein promoting cell survival, in part, by activating the canonical NF-kappa-B pathway (By similarity). Kinase activity is essential to regulate necroptosis and apoptosis, two parallel forms of cell death: upon activation of its protein kinase activity, regulates assembly of two death-inducing complexes, namely complex IIa (RIPK1-FADD-CASP8), which drives apoptosis, and the complex IIb (RIPK1-RIPK3-MLKL), which drives necroptosis (By similarity). RIPK1 is required to limit CASP8-dependent TNFR1-induced apoptosis (By similarity). In normal conditions, RIPK1 acts as an inhibitor of RIPK3-dependent necroptosis, a process mediated by RIPK3 component of complex IIb, which catalyzes phosphorylation of MLKL upon induction by ZBP1. Inhibits RIPK3-mediated necroptosis via FADD-mediated recruitment of CASP8, which cleaves RIPK1 and limits TNF-induced necroptosis. Required to inhibit apoptosis and necroptosis during embryonic development: acts by preventing the interaction of TRADD with FADD thereby limiting aberrant activation of CASP8 (By similarity). In addition to apoptosis and necroptosis, also involved in inflammatory response by promoting transcriptional production of pro-inflammatory cytokines, such as interleukin-6 (IL6). Phosphorylates RIPK3: RIPK1 and RIPK3 undergo reciprocal auto- and trans-phosphorylation. Phosphorylates DAB2IP at 'Ser-728' in a TNF-dependent manner, and thereby activates the MAP3K5-JNK apoptotic cascade. Required for ZBP1-induced NF-kappa-B activation in response to DNA damage (By similarity).
Synonyms: RIP-1; RIP; RIP1; AIEFL; IMD57
Tractability: Small molecule: a drug acting on it is in phase 2 or 3 trials; a structure with a bound ligand is known; a high-quality ligand is known; it belongs to a druggable protein family. Antibody: its Gene Ontology location is reachable by antibodies, with high confidence; UniProt places it where antibodies can reach, with medium confidence; the Human Protein Atlas places it where antibodies can reach. PROTAC: it is named in the literature on targeted protein degradation; UniProt records ubiquitination sites on it; ubiquitination databases record sites on it; its protein half-life has been measured; a small molecule that binds it is known.
Target class: TKL protein kinase group; Enzyme; Kinase; TKL protein kinase RIPK family; Protein Kinase
Chemical probes: GSK-2982772 (high quality), GSK481 (high quality), TP-030-1 (high quality), TP-030-2 (high quality)
Gene: Protein-coding gene on chromosome 6 (3,063,824 to 3,115,187, forward strand). Ensembl gene ENSG00000137275.
Subcellular location: Cytoplasm; Cell membrane
Subcellular location (Human Protein Atlas): Cytosol; Plasma membrane
Pathways (Reactome):
Immune System: IKK complex recruitment mediated by RIP1; NF-kB activation through FADD/RIP-1 pathway mediated by caspase-8 and -10; RIP-mediated NFkB activation via ZBP1; TICAM1, RIP1-mediated IKK complex recruitment; TLR3-mediated TICAM1-dependent programmed cell death; TRIF-mediated programmed cell death
Programmed Cell Death: CASP8 activity is inhibited; Caspase activation via Death Receptors in the presence of ligand; Dimerization of procaspase-8; RIPK1-mediated regulated necrosis; Regulation by c-FLIP; Regulation of necroptotic cell death
Disease: Defective RIPK1-mediated regulated necrosis; Dengue virus modulates apoptosis; Microbial modulation of RIPK1-mediated regulated necrosis; Potential therapeutics for SARS; SARS-CoV-1-mediated effects on programmed cell death
Signal Transduction: Regulation of TNFR1 signaling; TNF signaling; TNFR1-induced NF-kappa-B signaling pathway; TNFR1-induced proapoptotic signaling
Metabolism of proteins: Ovarian tumor domain proteases; Ub-specific processing proteases
Transport of small molecules: TRP channels
Gene Ontology:
Molecular function: death domain binding; death receptor binding; identical protein binding; protein binding; protein homodimerization activity; protein kinase activity; protein serine kinase activity; protein serine/threonine kinase activity; protein serine/threonine kinase binding; protein-containing complex binding; ubiquitin protein ligase binding; JUN kinase kinase kinase activity; ATP binding; protein serine/threonine phosphatase activity; signaling adaptor activity
Biological process: activation of protein kinase activity; amyloid fibril formation; apoptotic process; canonical NF-kappaB signal transduction; cellular response to tumor necrosis factor; extrinsic apoptotic signaling pathway; intracellular signal transduction; necroptotic process; necroptotic signaling pathway; negative regulation of canonical NF-kappaB signal transduction; negative regulation of extrinsic apoptotic signaling pathway; positive regulation of apoptotic process; positive regulation of canonical NF-kappaB signal transduction; positive regulation of extrinsic apoptotic signaling pathway; positive regulation of gene expression; positive regulation of inflammatory response; positive regulation of interleukin-6-mediated signaling pathway; positive regulation of interleukin-8 production; positive regulation of JNK cascade; positive regulation of macrophage differentiation; positive regulation of miRNA processing; positive regulation of necroptotic process; positive regulation of programmed cell death; positive regulation of programmed necrotic cell death; positive regulation of transcription by RNA polymerase II; and 26 more
Cellular component: death-inducing signaling complex; mitochondrion; protein-containing complex; receptor complex; ripoptosome; cytoplasm; cytosol; endosome membrane; plasma membrane; tumor necrosis factor receptor superfamily complex
Genetic constraint (gnomAD): Loss-of-function variants: 21 observed, 50.37 expected, observed/expected ratio (o/e) 0.42, 90% interval 0.29 to 0.6. The upper end of that interval is the gene's LOEUF score, 0.6, which puts it in group 2 of 6, group 1 being the genes least tolerant of losing a copy. Missense variants: 603 observed, 726.99 expected, observed/expected ratio (o/e) 0.83, 90% interval 0.77 to 0.89. Synonymous variants: 250 observed, 271.87 expected, observed/expected ratio (o/e) 0.92, 90% interval 0.83 to 1.02.
Gene-disease validity (ClinGen):
ClinGen rates the evidence that RIPK1 causes each of these diseases.
immunodeficiency 57 (autosomal recessive): Definitive.
Homologues: Orthologues: chimpanzee RIPK1 (99% identical), macaque RIPK1 (94% identical), dog RIPK1 (78% identical), rabbit RIPK1 (77% identical), pig RIPK1 (73% identical), rat Ripk1 (70% identical), mouse Ripk1 (70% identical), guinea pig RIPK1 (68% identical), tropical clawed frog ripk1 (43% identical), zebrafish ripk1l (38% identical). Paralogues in human: MAP3K9 (17% identical), MAP3K10 (17% identical), MAP3K21 (17% identical), TESK2 (16% identical), MAP3K11 (15% identical), MAP3K20 (15% identical), MAP3K12 (15% identical), MAP3K13 (15% identical), TESK1 (15% identical), LRRK2 (15% identical), RIPK2 (14% identical), RIPK3 (12% identical), and 11 more.
Diseases named in the same sentence as RIPK1 in open-access papers:
RIPK1 is named in the same sentence as 349 diseases in open-access papers, as found by Europe PMC text mining. Sharing a sentence is not in itself a finding about the gene and the disease. The quoted sentences say what the papers report.
viral infection (48 papers, 2015 to 2025). "To pursue investigations on the role of RIPK1 during viral hepatitis, we exposed Ripk1LPC-KO and Ripk1fl/fl mice to a molecular pattern associated with viral infection, the poly I:C." (PMID 30622241, 2019). "This cell death pathway is typically initiated when apoptosis is inhibited, such as during viral infection or caspase-8 dysfunction, and involves receptor-interacting protein kinase 1 (RIPK1), RIPK3, and mixed-lineage kinase domain-like pseudokinase (MLKL)." (PMID 40771812, 2025). "Under virus infection, which promotes Ripk1-dependent necrosis by stimulating tumor necrosis factor (TNF), Ripk3 subsequently induced the phosphorylation of Ripk1, which resulted in the formation of a pro-necrotic necrosome complex." (PMID 36849513, 2023). "At this point, however, there is still a limited understanding of the specific effects of RIPK1 inhibition in disease pathogenesis during viral infections." (PMID 34372694, 2021). "Upon activation by death receptor stimulation or by viral infection, RIPK1 complexes with RIPK3 through a RIP homotypic interacting motif (RHIM) and induces downstream signaling." (PMID 34502533, 2021). "Although Zbp1 has not yet been studied as an atherosclerosis modifier, it has a role as a sensor of viral infections, in NLRP3 regulation after viral infection, and a role in necroptosis and inflammation via its effects on the RIPK1, RIPK3, and MLKL pathways." (PMID 35052410, 2021). "In most viral infections, RIPK1-mediated signaling protects the host by inducing either cell death or secretion of inflammatory cytokines and IFN, as illustrated by the studies of WNV, ZIKV, and VACV infection of RIPK1 kinase activity-deficient mice." (PMID 34372694, 2021). "Considering that RIPK1 mediates necroptosis along with inflammasome activation upon virus infection, and the inflammasome activation can lead to pyroptosis, it is possible that both cell death pathways are activated to a certain extent in SIV-infected PAMs." (PMID 30096906, 2018). "Several viral infections have been shown to initiate RIPK1/3 mediated necroptosis, which contributes to host immunity against the infection." (PMID 28410401, 2017). "The importance of RIPKs in combating viral infections is further highlighted by the fact that both RIPK1 and RIPK2 are known ISGs." (PMID 26297639, 2015). "To explore whether the essential role of RIPK1 in ZBP1 activation during viral infection involves TNF signaling, we treated HT29-hZBP1 cells with or without TNF-neutralizing antibody during HSV-1(ICP6mut) infection." (PMID 39982916, 2025). "Recent studies have reported that RIPK1 kinase activity is not universally required for all necroptosis instances, as RIPK3 can be activated independently of RIPK1 by external stimuli, such as viral infection, heatstroke, and osmotic stress, which activate RIPK3 via Z-DNA-binding protein 1 (ZBP1)." (PMID 40221399, 2025). "To determine whether RIPK1 binds to ZBP1 during viral infection, we used the FLAG antibody to immunoprecipitate FLAG-ZBP1 from infected HT29-hZBP1 cells." (PMID 39345610, 2024). "Lastly, viral infection elicits the production of TNF that can act in an autocrine/paracrine manner to initiate apoptosis in the presence of functional caspase-8, or necroptosis via the association of RIPK1 with RIPK3 in its absence." (PMID 35549723, 2022). "Understanding the impact of inhibition of RIPK1 signaling on the host and the virus may facilitate the development of new immunotherapeutic strategies against virus infections." (PMID 34372694, 2021). "It is not until T cells become activated that RIPK1 can additionally mediate host defense functions by triggering necroptosis in susceptible cells, for instance during viral infections." (PMID 30737145, 2019).
viral infection (continued). "Although the dual function of RIPK1 is best understood in the context of TNFα signaling, a wide range of other triggers, such as IFNαR, TLRs, viral infection, and genotoxic stress have recently been described to trigger RIPK1 activation and necrosome formation." (PMID 30250197, 2018). "The cellular and molecular basis of viral disease in RIPK1 deficiency has yet to be studied, and it is unclear whether RIPK1 deficiency affects non-leukocytic, cell-intrinsic immunity to viruses." (PMID 37083451, 2023). "The RIPK1-dependent cell death activation might be influenced by viral infections." (PMID 35390032, 2022). "Cuchet-Lourenço and colleagues reported 3 siblings (One was sequenced and found to harbor a RIPK1 mutation and the others with the presumable same mutation) that underwent HSCT; two of them died within weeks of the procedure due to multi-organ failure or disseminated viral infections." (PMID 36466854, 2022). "ZBP1 can sense viral infections and activate RIPK3, thus inducing RIPK1-independent activation of necroptosis." (PMID 40261527, 2025). "Ponatinib, which is reported to directly target and inhibit RIPK1 and RIPK3, can protect HCs from damage by viral infections." (PMID 40261527, 2025). "If it is found that pathogenic CoVs do indeed produce Z-RNA (as the ZH3 algorithm predicts) and that the RHIM in Nsp13 regulates ZBP1, RIPK3, RIPK1, TRIF or SMG1 signaling, then we suggest that effects will depend on the stage of viral infection." (PMID 35784331, 2022). "Of note, necroptosis can be elicited in a RIPK1-independent way, using Toll-like receptors (TLR) 3 and 4, or viral infections via acid nucleic sensors recruiting the RIPK3-MLKL axis." (PMID 36613804, 2022). "An initial study on DRP1-mediated NLRP3 inflammasome activation upon viral infection discovered that in response to vesicular stomatitis virus (VSV), RIPK1 forms a complex with RIPK3 to induce necroptosis, while it also phosphorylates DRP1." (PMID 30096906, 2018). "The common modulation of these pro-apoptotic proteins supports the data presented herein, that the cleavage of RIPK1 by HRV is imperative to changing host responses and establishing viral infection." (PMID 29371673, 2018). "For instance, RIPK1 was shown to be essential in inducing inflammatory cytokines (IL-6, IL-1β, TNF-α) in response to bacterial and viral infections." (PMID 28410401, 2017). "RIPK1 interactions with TLR3 or DAI are mediated by RHIM and play important roles during virus infection." (PMID 26297639, 2015). "N-terminal cleavage products appeared 24 h after infection showing that RIPK1 and RIPK2 are cleaved during virus infection." (PMID 26297639, 2015). "Zebrafish receptor (TNFRSF)-interacting serine-threonine kinase 1 (ripk1l) is orthologous to human RIPK1, which participates in Toll-like receptor (TLR) and retinoic acid-inducible gene I (RIG-I) signaling following viral infection and which was upregulated with mVenus-PR8 infection." (PMID 38275965, 2024). "Similar to MEF-mZBP1 cells, hZBP1-mRIPK3 complex formation during viral infection is independent of RIPK1 and resistant to 4M treatment, indicating that mRIPK3 tends to form a more stable complex with ZBP1 compared to hRIPK3." (PMID 39345610, 2024). "Concerning mechanism, we found that the transcription of TNF-α was increased in PRV-infected PK-15 cells, whereas classical RIPK1 was not related to necroptosis during viral infection." (PMID 34149651, 2021). "As for DDX58, NFκB1, TOLLIP, RIPK1, DDX3Y, TRIM25 and JAK2, which are involved in antiviral signalling transduction, both increased mRNA abundance and switched poly(A) sites eventually led to enhanced protein production following viral infection." (PMID 28233779, 2017). "Interestingly, the receptor interacting serine/threonine protein kinase (RIPK) family members (RIPK1 and RIPK3) regulate necroptosis (a form of programmed necrosis) and play a critical role in immunity to viral infections." (PMID 28410401, 2017).
viral infection (continued). "Notably, treatment with R1-ICR-3 initiated necroptosis in SVEC4-10 and 3T3-SA cells, independent of viral infection, suggesting the inhibitory role of RIPK1 on ZBP1-initiated necroptosis in mouse cells." (PMID 39982916, 2025). "Conversely, inhibitors targeting caspase-9, pan-caspases, NLRP3 inflammasome, and RIPK1 significantly suppressed NF-κB activation, suggesting that these pathways are involved in the negative regulation of NF-κB activation during IBV infection, as previously suggested for other viral infections." (PMID 40284946, 2025). "Furthermore, RIPK1 inhibition in IBV Conn A5968-infected cells enhanced caspase-1 activity, suggesting a potential crosstalk between RIPK1 and NLRP3 pathways in regulating caspase-1 activity, as described in other viral infection models." (PMID 40284946, 2025). "Moreover, the increased expression of necrosis‐related proteins (p‐MLKL, RIPK1, and RIPK3) induced by viral infection was reduced by pyrogallol, suggesting that pyrogallol could alleviate H1N1 virus‐triggered necrosis." (PMID 38617435, 2024). "Indeed, in mouse models, RIPK1 inhibitors have been shown to prevent or alleviate clinical symptoms of various diseases, including SIRS, ischemia-induced tissue injury, neurodegeneration, and bacterial and viral infections." (PMID 39062098, 2024). "This cleavage may disrupt the function of RIPK1, as a co-overexpression of RIPK1 and HIV-1 PR in HEK293T cells resulted in a diminished ability of RIPK1 to activate NF-κB; however, the disruption of RIPK1 function during viral infection was not tested." (PMID 35746649, 2022). "The ActoD generated RIPK1 cleavage product was distinct from that seen in infection alone samples, showing that RIPK1 cleavage products detected in infected samples were not due to an apoptotic response to virus infection." (PMID 34960671, 2021). "While this pathway is also critical for other death factors, such as FasL or TRAIL, -induced necroptosis, RIPK1 is not involved in viral infection and Toll-like receptor (TLR)-mediated necroptosis, although RIPK3 and MLKL seem to be the common players of necroptosis." (PMID 33976222, 2021). "Indeed, consistent with the cell viability assay, RIPK1 co-immunoprecipitated with ZBP1 and RIPK3 in necroptosis-susceptible cells (HT29 WT, mutZα1, and mutRHIMB) following viral infection but was not in cells with inactivating mutations in Zα2 or RHIM A (mutZα2, mutZα1Zα2, and mutRHIMA)." (PMID 39345610, 2024). "However, since inhibition of RIPK1 by Nec-1s did not reduce viral loads in HeLa cells stably expressing ACE2 or in Huh7 cells which show a reduction of ACE2 upon viral infection, Nec-1s is not likely acting as a direct inhibitor of the RdRp replication machinery." (PMID 34663909, 2021). "Using an inhibitor of RIPK1 to pre-treat cells, necroptosis was not affected after viral infection indicating that the ZIKV-induced necroptosis was not RIPK1 dependent and neither RIPK3 nor necrosome was probably not activated by RIPK1 in astrocytes." (PMID 33796483, 2021). "In contrast, the expression of Cre in WT MEF cells did not affect the expression level of TAK1 or RIPK1 S321 phosphorylation in response to TNFα, suggesting the blocked RIPK1 S321 phosphorylation in TAK1F/F Cre MEFs was not a result of virus infection or Cre expression per se." (PMID 28842570, 2017).